INS (insulin)
Diseases named in the same sentence as INS in open-access papers (continued):
Sharing a sentence is not in itself a finding about the gene and the disease.
Insulin resistance (continued). "At 12 weeks old, their body weight, fasting blood glucose (FBG), blood insulin level (IRI), homeostatic model assessment for insulin resistance (HOMA-IR), liver lipid metabolism gene expression, and liver metabolites were compared." (PMID 38892554, 2024). "The increased anabolic functions mediated by hepatic insulin resistance result in elevated FFA concentrations, increased gluconeogenesis, disruption of insulin sensitivity in adipocytes, and increased lipogenesis." (PMID 39064282, 2024). "Obesity contributes to insulin resistance, a critical factor in the onset of T2DM, as excess fat tissue diminishes the cells’ responsiveness to insulin." (PMID 39596023, 2024). "Insulin resistance was moderate in WT mice fed the HFD and in Foz mice on ND as supported by the levels of both insulin and glucose." (PMID 39206703, 2024). "Fasting insulin and the homeostasis model assessment of insulin resistance (HOMA-IR) index are relatively simple and reliable noninvasive markers of insulin resistance (IR)." (PMID 39529982, 2024). "In this study, we monitored the dynamic insulin response in rats via insulin tolerance tests and computed the HOMA-IR index as a static measure of insulin resistance." (PMID 38724553, 2024). "Neonatal glucose and insulin concentrations were estimated, and indices of IR such as homeostatic model assessment for insulin resistance (HOMA-IR), quantitative insulin-sensitivity check index (QUICKI), and glucose-to-insulin ratio were calculated." (PMID 38469369, 2024). "Cinnamon extract also ameliorated insulin sensitivity by increasing quantitative insulin sensitivity check index (QUICKI) (p < 0.03) and the Matsuda insulin resistance index (p < 0.05), as well as reducing HOMA-IR (p < 0.03), compared to baseline." (PMID 39796448, 2024). "Serum glucose and insulin levels were measured during the glucose tolerance and insulin tolerance tests to evaluate PBC function and insulin resistance." (PMID 38172956, 2024). "DKO male mice showed severe glucose intolerance and insulin resistance and AF1 peptide treatment significantly improved glucose homeostasis and insulin sensitivity in DKO male mice." (PMID 38649684, 2024). "Fasting glucose and Insulin resistance (IR) markers HOMA-IR (Homeostasis model assessment of insulin resistance) and QUICKI (Quantitative insulin sensitivity check index) have been shown to be more altered in adolescents with PCOS compared to controls." (PMID 39415788, 2024). "Both groups had their HA1c and blood sugar levels measured; group A had their insulin, GLP-1, and HOMA-IR (Homeostasis Model Assessment for Insulin Resistance) levels calculated at time O and one year later." (PMID 38369509, 2024). "The hyperinsulinemia and lower insulin sensitivity observed in our study participants in the absence of overt hyperglycemia suggest that FGFR1 signaling may be temporally implicated in the early insulin hypersecretory phase and insulin resistance seen in initial stages of T2D pathophysiology." (PMID 38957656, 2024). "The hypothesis is that high post-load glucose levels in individuals with normal fasting and post-load glucose are associated with increased cardiovascular disease risk due to the pro-inflammatory state, regardless of insulin resistance and impaired insulin secretion." (PMID 38389086, 2024). "Obesity can exacerbate insulin resistance, a common feature of PCOS, leading to increased levels of insulin and androgens." (PMID 38567220, 2024). "As insulin resistance is a significant pathogenetic factor in MASH16, insulin administration has beneficial effects on liver pathology and expression of genes related to inflammation and fibrosis." (PMID 39131144, 2024). "Elevated NCOR2 levels increase insulin (INS) production, which subsequently decreases INSR expression and AKT phosphorylation (p-AKT), leading to the development of insulin resistance and ultimately hyperglycemia." (PMID 39337631, 2024).
Insulin resistance (continued). "Guo and Xu reported that insulin resistance is positively correlated with SUA in women (p < 0.05) and that insulin sensitivity is lower in postmenopausal women than in premenopausal women." (PMID 39469332, 2024). "Serum glucose, insulin and NEFA levels were significantly higher in the OC group than in the LC cohort, suggesting insulin resistance." (PMID 38539902, 2024). "In this study, we aimed to longitudinally investigate the factors associated with a 4-year body weight change, including serum insulin concentration and HOMA-IR, as a surrogate measure of insulin resistance, in a comprehensive general population cohort." (PMID 38649714, 2024). "Insulin resistance in T2DM disrupts metabolic signaling, impairing the regulatory effects of insulin on THBS1 and promoting inflammation, further increasing THBS1 concentration." (PMID 39050565, 2024). "After the investigation, body weight, fasting blood sugar (FBS), irisin, insulin, C‐reactive protein (CRP), interleukin‐6 (IL‐6), interleukin‐1 beta (IL‐1β), leptin, adiponectin, and insulin resistance (IR) were assessed." (PMID 39479712, 2024). "In previous studies, C2C12 cells appear to be the most frequently used cell type for in vitro construction of muscle insulin resistance models (a total of 666 papers in PUBMED searching, using the key words “C2C12 cells, insulin resistance”)." (PMID 39749015, 2024). "Current studies have shown that in addition to insulin resistance (IR) during pregnancy, there are many other factors affecting the occurrence of GDM, including genetic factors, lifestyle, abnormal insulin secretion, and fetal factors." (PMID 39220593, 2024). "Nutritional approaches, particularly low-glycemic index diets and those rich in fibre, can enhance insulin sensitivity and assist in weight management, a critical component in managing PCOS-related insulin resistance." (PMID 39276209, 2024). "Their potential for managing T2DM can be evaluated by assessing their effects on fasting blood glucose (FPG), glycated hemoglobin (HbA1c), homeostatic model assessment for insulin resistance (HOMA-IR), and fasting serum insulin (FSI)." (PMID 39413550, 2024). "It is also possible that insulin resistance is the link between low GH levels and MASLD, as insulin directly suppresses pituitary GH secretion." (PMID 39665021, 2024). "Patients had greater fasting glucose and insulin levels, indicating that they acquired T2DM and insulin resistance as the condition progressed." (PMID 39202691, 2024). "In streptozotocin-induced experimental type 2 diabetic rats fed a high-fat diet, GA significantly reduced plasma insulin and HOMA-IR levels and normalised changes in insulin resistance levels, thereby reducing body weight and fasting blood glucose." (PMID 39840111, 2024). "DM is identified by the abnormally excessive blood glucose level as a result of inadequate insulin secretion, called type 1 DM (DM1), or insulin resistance, called type 2 DM (DM2)." (PMID 39011437, 2024). "Elevated leptin and PAI-1 levels exacerbate insulin resistance, interfere with IRS-1, and negatively impact insulin signaling in PLT membranes." (PMID 39858414, 2024). "In an animal model of sucrose-induced insulin resistance, it has been demonstrated that dietary GLY supplementation decreases liver OxS biomarkers, increases liver GSH, and improves insulin sensitivity." (PMID 38397782, 2024). "Insulin resistance (HOMA-IR) showed significant increasing trend and insulin sensitivity (Matsuda index) shown significant deceasing trend among three groups of NOH, MHO and MUHO in both baseline and follow up visits (p-value < 0.001 in linear trend)." (PMID 38548792, 2024). "Finally, reduced Pparg expression has been noted in adipocytes from insulin resistant humans and rodents, but whether this causes insulin resistance is not known." (PMID 38816388, 2024).
Insulin resistance (continued). "Fasting insulin (FINS) and C-peptide were negatively correlated with SCr (p < 0.05), and the homeostatic model assessment of insulin resistance (HOMA-IR) was positively correlated with SCr (p < 0.05)." (PMID 38414619, 2024). "Insulin signaling is thus suppressed downstream of the insulin receptor (IR) at the level of IR substrate-1 (IRS-1) and PI3K, which together promote insulin resistance in peripheral tissues." (PMID 38255314, 2024). "A logistic regression analysis was conducted to evaluate the likelihood of DPN based on several predictors including fasting glucose, fasting insulin, VEGF, adiponectin, HbA1C, and insulin resistance." (PMID 38410303, 2024). "Common clinical detection techniques include direct and indirect methods such as the hyperinsulinemic-euglycemic clamp technique, the Quantitative Insulin Sensitivity Check Index (QUICKI), and the homeostasis model assessment of insulin resistance (HOMA-IR)." (PMID 39717101, 2024). "In this study, HFD‐fed obese mice had significantly higher FBG and insulin levels, as well as HOMA‐IR values, than NCD‐fed non‐obese mice, suggesting the occurrence of glucose intolerance and insulin resistance." (PMID 39554331, 2024). "Many previous meta-analyses have confirmed that resveratrol can improve insulin resistance in T2DM patients, reduce fasting blood glucose and insulin levels, improve cardiometabolic parameters, and improve blood lipids." (PMID 39872318, 2024). "In addition, some pathways such as calcium metabolism, inflammatory cytokine production, and adipocyte modulation may reinforce this susceptibility axis of FokI in the mechanism surrounding DM development, being pointed out as a gene that is involved in insulin secretion for insulin resistance." (PMID 38812030, 2024). "Probiotics also decrease insulin resistance, reduce triglyceride, cholesterol and LDL concentration, improve insulin sensitivity and glucose homeostasis and also lower hepatic steatosis." (PMID 38504163, 2024). "This appears to relate to the progression of hepatic insulin resistance, which reduces the suppression of the hepatokine IGFBP-1 relative to circulating insulin levels." (PMID 38928106, 2024). "In vitro, betaine reversed insulin resistance by increasing insulin-stimulated tyrosine phosphorylation of IRS1 and activation of downstream proteins in the insulin signaling cascade in insulin resistant primary human hepatocytes." (PMID 39119463, 2024). "Other methods to measure IR, such as homeostatic model assessment for insulin resistance (HOMA-IR) and quantitative insulin sensitivity check index (QUICKI) are based on the measurement of fasting insulin and glucose." (PMID 39906033, 2024). "Furthermore, insulin resistance is a hallmark clinical feature in PCOS patients, which may culminate in elevated fasting insulin levels, potentially contributing to the development of polycystic follicles and ovulatory complications, thereby exacerbating the clinical presentation of PCOS." (PMID 38779450, 2024). "Moreover, Kristin and colleagues found that SIRT4 could control leucine metabolism through regulating the acylation levels of enzymes in the pathway, and mice lacking Sirt4 have dysregulated leucine metabolism that can lead to increased insulin and development of age-induced insulin resistance." (PMID 39372420, 2024). "The binding of holo-RBP4 to STRA6, the cell surface receptor of RBP4, directly inhibits insulin signaling by activating the JAK2/STAT5/SOCS3 pathway, leading to insulin resistance." (PMID 38520616, 2024). "Pro-inflammatory cytokines showed a correlation with insulin resistance in adipocytes, especially TNF-α, a major mediator in the development of chronic inflammation that leads to a reduction in insulin-induced glucose uptake ability." (PMID 38543073, 2024).
Insulin resistance (continued). "However, it is hypothesized that iron overload may contribute to insulin resistance and impaired glucose tolerance through mechanisms such as oxidative damage to pancreatic beta cells and interference with insulin's ability to suppress hepatic glucose production." (PMID 39583387, 2024). "As expected, insulin sensitivity was increased by BPV and the olive oil induced insulin resistance was prevented." (PMID 38578954, 2024). "Increased DAG levels inhibit PKC, leading to defective activation of IRS-1/PI3K/AKT insulin signaling, downregulation of GLUT4 and forthcoming insulin resistance." (PMID 39728000, 2024). "Cells with developed insulin resistance (IR+ ethanol, IR + DMSO) showed only a slight increase in ISGU in insulin-treated cells (INS+) compared to BGU (INS−)." (PMID 39339765, 2024). "Insulin sensitivity estimated by HOMA-IR and the Matsuda index during MMT revealed that HFD-feeding resulted in a significantly increased insulin resistance compared to chow." (PMID 38427692, 2024). "RS-fed mice showed lower fasting insulin levels (p < .1) and decreased homeostatic model assessment for insulin resistance (HOMA-IR, p < .0001), suggesting that RS improved insulin resistance." (PMID 38873438, 2024). "Fasting insulin levels and HOMA-IR were utilized as surrogate markers for insulin resistance, deviating from the gold standard hyperinsulinemic-euglycemic clamp study." (PMID 38846245, 2024). "Physiologically, insulin resistance increases during pregnancy, however, GDM and maternal hyperglycemia arise in case of an insufficient insulin response combined with a relative beta-cell dysfunction." (PMID 39497166, 2024). "In particular, resistin, leptin, and PAI-1 induce insulin resistance by interfering with the expression of insulin receptor substrate-1 (IRS-1), negatively impacting insulin signaling in PLTs." (PMID 39858414, 2024). "One commonly used indicator of insulin resistance in clinical research is the homeostatic model assessment for insulin resistance (HOMA-IR), which is based on fasting glucose and fasting insulin levels." (PMID 39768947, 2024). "Studies indicate that insulin exerts a regulatory influence on SHBG biosynthesis, showing an inverse relationship with insulin resistance." (PMID 39876919, 2024). "Studies suggest that METS-IR provides a more precise prediction of insulin sensitivity, surpassed only by the euglycemic-hyperinsulinemic clamp (EHC), the gold standard for insulin resistance measurement." (PMID 39830199, 2024). "Moreover, insulin tends to increase under the impact of gestational hormones during pregnancy, especially in the case of high parity after two children, which could result in accumulating physiological changes, such as progressive insulin resistance." (PMID 38745759, 2024). "Our studies highlight the need to consider the interdependence between insulin-dependent inhibition of fatty acid oxidation and activation of PDH when exploring mechanisms responsible for insulin resistance and diminished glucose oxidation." (PMID 38796064, 2024). "A positive correlation was found between ANGPTL3 and plasma glucose, insulin, and HOMA-IR levels in patients with insulin resistance, and its levels were higher in patients with NASH/MASH than in patients with simple steatosis." (PMID 39409124, 2024). "To evaluate insulin sensitivity, we calculated 2 parameters: the homeostatic model assessment for insulin resistance (HOMA-IR) and the quantitative insulin sensitivity check index (QUICKI)." (PMID 39050819, 2024). "Insulin resistance may be linked to systemic chronic inflammation related to obesity, where inflammatory factors can impede the phosphorylation of the insulin receptor substrate and PI3K in the insulin signaling pathway, resulting in obstructed signal transduction and insulin resistance." (PMID 38167106, 2024).
Insulin resistance (continued). "In rats with pancreatic disorder and dexamethasone-induced insulin resistance, crocetin reduced free fatty acids, triglyceride, and TNF-α, and increased insulin secretion by reinforcing pancreatic islet beta cells." (PMID 38419885, 2024). "Two well-known milk protein-derived peptides, IPP and VPP, demonstrated effective enhancement of insulin signals and anti-inflammation via the NF-κB pathway under TNF stimulation and prevention of insulin resistance." (PMID 38672494, 2024). "There is existing evidence suggesting cross-talk between OCN and insulin resistance in animal models, where OCN expression contributes to the regulation of insulin production and reduction in visceral adiposity." (PMID 38731059, 2024). "PPM1α overexpression in the liver showed great improvement in insulin sensitivity under statin treatment and further lipid metabolism, suggesting that liver‐specific PPM1α overexpression could be used as a treatment for insulin resistance or even other metabolic syndromes." (PMID 38970167, 2024). "However, an association between serum myostatin levels and insulin sensitivity independent of body composition and other risk factors for insulin resistance, namely higher BMI, higher VAT, and male sex, has not been reported using a validated myostatin LC–MS/MS assay." (PMID 39261976, 2024). "Overt hepatic insulin resistance in individuals with poorly controlled T1DM was suggested, and the reason for this is that the effect of insulin is suppressed by plasma FFAs." (PMID 38732629, 2024). "The insulin resistance (IR) parameter (HOMA2IR), beta-cell function percentage (HOMA2%B), and insulin sensitivity (HOMA2%S) were all determined by the Homeostasis Model Assessment-2 (HOMA2) calculator." (PMID 39335530, 2024). "Notably, β cells from BoNT/BTan mice exhibited elevated expression of the early onset ER-stress marker Atf4, suggesting that the increased insulin secretion observed in these mice following insulin resistance may trigger an ER unfolded protein response and ER stress." (PMID 39047908, 2024). "Fifth, the HOMA-IR, or revised quantitative insulin sensitivity check index (QUICKI), is the most widely used surrogate measure of insulin resistance." (PMID 38463431, 2024). "The possible cause of the association between the Gutt index and two-hour glucose levels with stroke risk, while fasting insulin levels do not, may be attributed to the fact that peripheral insulin resistance might have a higher correlation with cardiovascular risk factors among older individuals." (PMID 39347227, 2024). "Taken together, our data indicated that HFD mice developed insulin resistance (IR) as exhibited by the increased blood glucose levels of IPGTT and impaired insulin signaling." (PMID 39616329, 2024). "The ITT results showed that the AUC in the HFD group was significantly higher than in the CON group (t=34.01, p<0.001), suggesting that the insulin sensitivity of the HFD group mice decreased, indicating that the HFD-fed mice developed insulin resistance." (PMID 39211822, 2024). "The insulin pathway, central to glucose metabolism, is often disrupted in NAFLD, leading to insulin resistance." (PMID 38893506, 2024). "Compared with their control littermates, HFD-Anxa1AKO mice exhibited glucose intolerance and insulin resistance, implying that ANXA1 was also essential for glucose regulation and for influencing insulin sensitivity in peripheral tissues." (PMID 39174522, 2024). "Insulin resistance was assessed using HOMA-IR (Homeostatic Model Assessment for Insulin Resistance), by the formula: fasting insulin (microU/L) × fasting glucose (nmol/L) / 22.5." (PMID 38722393, 2024). "Other animal experiments have demonstrated that the insulin-stimulating peptide D-Ala2-GIP-glu-PAL increases insulin secretion and reduces insulin resistance." (PMID 38818523, 2024).